BCL2 (BCL2 apoptosis regulator)
Diseases named in the same sentence as BCL2 in open-access papers (continued):
Sharing a sentence is not in itself a finding about the gene and the disease.
acute myeloid leukemia (continued). "For instance, the METTL3 and METTL14, highly expressed in acute myeloid leukemia (AML), play a critical role in leukemia progression through promoting translation of target mRNAs, including MYB, MYC, BCL2, and PTEN." (PMID 33292652, 2020). "B‐cell lymphoma 2 (BCL‐2), a crucial member of the anti‐apoptotic BCL‐2 family, is frequently dysregulated in cancer and plays an important role in acute myeloid leukemia (AML)." (PMID 32519423, 2020). "Overexpression of BCL-2, BCLXL, and MCL1 frequently occurs in acute myeloid leukemia (AML) conferring resistance to conventional chemotherapy." (PMID 33230098, 2020). "The BCL2 inhibitor (BCL2i) venetoclax has shown significant benefical activity in CLL and acute myeloid leukemia (AML), but the therapeutic effects in DLBCL are still under investigation." (PMID 33260693, 2020). "The BCL-2 specific inhibitor venetoclax (ABT-199) was the first compound in this field that became approved by the United States Food and Drug Administration (FDA) for treatment of chronic lymphocytic leukemia (CLL) and selected acute myeloid leukemia (AML) patients." (PMID 33070156, 2020). "Venetoclax (ven), a pro‐apoptotic Bcl‐2 inhibitor, is an oral agent that can be used in various combinations as the standard of care in patients with acute myeloid leukemia (AML) who are not suitable for intensive chemotherapy." (PMID 41431240, 2025). "In the THP-1 model of acute myeloid leukemia (AML), neither the Bcl-2 inhibitor venetoclax nor cytarabine showed appreciable single-agent efficacy closely resembling the clinical experience in refractory AML patients." (PMID 39179926, 2024). "Several drugs directly target BCL2, among which venetoclax is the most promising, showing anti-tumor activity in a xenograft model of DLBCL and impressive response in patients with chronic lymphocytic leukemia (CLL) and acute myeloid leukemia (AML)." (PMID 38918775, 2024). "This study found that FGNs could treat acute myeloid leukemia subtype 2 (AML-M2) by silencing five essential oncogenes (BAG1, MDM2, Bcl-2, BIRC5, and XIAP) in AML-M2." (PMID 36612296, 2023). "Herein, we mainly discuss the BCL-2-specific BH3 mimetic venetoclax, the first United States Food and Drug Administration (FDA)-approved BCL-2 inhibitor, which has achieved revolutionary therapeutic advances in chronic lymphocytic leukemia (CLL) and acute myeloid leukemia (AML)." (PMID 37894324, 2023). "In acute myeloid leukemia (AML), overexpression of CPT1A indicates poor clinical prognosis, and strong synergistic inhibitory effects on AML were seen when the CPT1A-selective inhibitor ST1326 and the Bcl-2 inhibitor ABT199 were applied in combination." (PMID 37033619, 2023). "In support of the idea that targeting antiapoptotic Bcl-2 proteins with BH3 mimetics may increase NK cell-mediated cytotoxicity, a recent report has described that inhibition of Mcl-1, but not Bcl-2, increased the therapeutic efficiency of NK cells against acute myeloid leukemia (AML) cells." (PMID 34374809, 2022). "Moreover, in acute myeloid leukemia (AML) cells, METTL3 was abundantly expressed and promoted MYC, BCL2, and PTEN translation through m6A modification, which inhibited cell differentiation and fueled leukemia progression." (PMID 30518868, 2018). "The combination of Venetoclax (VEN), a BCL2 inhibitor, and Azacitidine (AZA), a hypomethylating agent, is the standard treatment for acute myelogenous leukemia (AML) in patients older than 65 years who are not eligible for intensive chemotherapy." (PMID 41615994, 2026). "Then, as the BCL2 anti-apoptosis factor is frequently overexpressed in NHL and specifically in DLBCL, we evaluated its expression profile in several cancer types (from the TCGA database) and we confirmed its overexpression specifically in DLBCL and acute myeloid leukemia (AML)." (PMID 41415285, 2025).
acute myeloid leukemia (continued). "For example, BCL2 and MYC, well-known oncogenes that inhibit apoptosis and promote cell proliferation, have been reported to undergo m6A-mediated translation, stabilization, or indirect promotion in bladder cancer, lung cancer, breast cancer, acute myeloid leukemia (AML), and gastric cancer." (PMID 40136363, 2025). "In a phase 1 study involving acute myeloid leukemia (AML) patients treated with G3139, no antisense-related toxicity was reported, and BCL2 downregulation was observed in patients who achieved complete remission." (PMID 39218979, 2024). "Venetoclax is a BCL-2 inhibitor that effectively improves clinical outcomes in newly diagnosed, relapsed and refractory acute myeloid leukemia (AML) patients, with complete response rates (with and without complete blood count recovery) ranging between 34–90% and 21–33%, respectively." (PMID 35884517, 2022). "Azacitidine, a hypomethylating agent, has caused a paradigm shift in the outcomes of patients with myelodysplastic syndrome (MDS) and acute myeloid leukemia (AML) who are not eligible for stem cell transplantation, particularly in combination with BCL2 and IDH inhibitors." (PMID 38406809, 2024). "There was a lack of expression of CK5/6, CD10, acute myeloid leukemia (AML), and BCL2." (PMID 29463294, 2018).
gastric cancer (392 papers, 1997 to 2026). A primary or metastatic malignant neoplasm involving the stomach. "Bcl-2’s overexpression in gastric cancer (GC) is consistently linked to high malignancy and poor patient survival." (PMID 40841912, 2025). "The same signaling pathway associated with upregulation of anti-apoptotic protein Bcl-2, downregulation of pro-apoptotic protein Bax, and increase in resistance to 5-FU, was activated in gastric cancer cells under the effect of CXCL5, produced by TAMs." (PMID 38794298, 2024). "EBV miR BART20-5p has been observed to favor chemoresistance to 5-FU and docetaxel in gastric cancer by targeting the pro-apoptotic BCL2-associated agonist of cell death (BAD) expression." (PMID 34745965, 2021). "ACE-induced gastric cancer cell death was associated with Bcl-2, survivin and Bax level changes, and it activated caspase-3 and -9." (PMID 33859522, 2021). "Increased levels of Bcl-2 expression have been also associated with resistance to different drugs including 5-fluorouracil in gastric cancer cisplatin in ovarian cancer and doxorubicin in osteosarcoma and chondrosarcoma." (PMID 32455818, 2020). "MiRNAs encoded by the miR-200bc/429 cluster has also been found to function as inhibitors of ADR- resistant gastric cancer cells through inhibiting expression of Bcl-2 and X-linked inhibitor of apoptosis (XIAP)." (PMID 32192494, 2020). "According to another study upregulation of Bcl-2 is caused by lower miR-15b and miR-16 expression level and leads to drug resistance in gastric cancer cells due to reduced apoptosis." (PMID 29967761, 2018). "Inhibition of proliferation and induction of apoptosis were caused by miR-1284’s inhibiting Bcl-2 expression in SGC-7901 gastric cancer cells." (PMID 29899164, 2018). "In a study of 501 Chinese GC patients after D2 gastrectomy, the less common Bcl-2 positive gastric cancers (22%) were significantly associated with better survival rates." (PMID 28662697, 2017). "In gastric cancer loss of miR-204 expression was associated with poor outcome, because it caused increase of antiapoptotic protein Bcl-2." (PMID 26126974, 2015). "For example, the Bcl-2 proto-oncogene is important in determining the susceptibility of tumor cells to apoptosis; with Bcl-2 expression and a high apoptotic fraction determined to be important prognostic factors of survival in advanced gastric cancer patients." (PMID 25788990, 2015). "Bcl-2 overexpression in gastric cancer tumors was shown to predict the loss of efficacy of chemotherapies based on 5-FU, MMC or ADM." (PMID 25019346, 2014). "In a previous study, we found that bcl-2 was significantly associated with prognosis in gastric cancer patients." (PMID 24555747, 2014). "The aim of this study was to evaluate the relationship between bcl-2 expression and risk of gastric cancer recurrence." (PMID 24555747, 2014). "Apoptosis of gastric carcinoma cells induced by isoalantolactone was associated with the dissipation of mitochondrial membrane potential due to downregulation of Bcl-2 and upregulation of Bax." (PMID 25003395, 2014). "Loss of miR-204 expression in gastric cancer has been associated with poor prognosis due to an increase in the anti-apoptotic protein, Bcl-2." (PMID 24025188, 2013). "We then sought to further delineate the mechanisms which underlie the combined effects of gastric cancer cell SF-CM on apoptosis-related proteins (caspase-3, caspase-8, Bax, bcl-2)." (PMID 22520554, 2012). "Previous studies have shown that the expression of bcl-2 was associated with better prognosis in non-small-cell lung cancer and gastric cancer." (PMID 22216342, 2011).
gastric cancer (continued). "Also, CBN has shown to increase Bax and reduce Bcl-2 expression and mitochondrial membrane potential, and cleavage of caspases 3 and 9 in a gastric cancer cell line, thereby causing apoptosis." (PMID 38802872, 2024). "In addition, hesperetin induced apoptosis in gastric cancer cells by activating the mitochondrial signaling pathway which caused the upregulation of Bax protein expression and down-regulating Bcl-2 expression." (PMID 34768743, 2021). "Failure in gastric cancer therapy may be the result of defective apoptosis process accompanied with the underlying mechanisms of Bcl-2 protein overexpression, hypoxia, and tumor microenvironment remodeling." (PMID 31817791, 2019). "In addition, the association of miR-1915-3p and Bcl-2 with clinicopathological features and prognosis of gastric cancer patients was evaluated." (PMID 31036603, 2019). "In addition, overexpression of UL138 greatly induced apoptotic cell death in different gastric cancer cells, in association with increased cleavage of apoptotic proteins caspase-3 and caspase-9 and reduction of an anti-apoptotic protein Bcl-2." (PMID 26735338, 2016). "Methylation of Bcl-2/adenovirus E1B 19-kDa-interacting protein 3 and death-associated protein kinase can predict a reduced response to chemotherapy and a poor prognosis in gastric cancer." (PMID 25788990, 2015). "Moreover, the signaling pathway is implicated in drug resistance in gastric cancer by regulating the expression of apoptotic proteins Bax (BCL2-associated X protein)/Bcl-2 (B-cell CLL/lymphoma 2)." (PMID 26692821, 2015). "Furthermore, many publications have shown that in neoplasms such as breast or stomach cancer, high levels of BCL2 proteins were associated with a worse prognosis." (PMID 22300941, 2012). "As a crucial carcinogen of gastric cancer, Helicobacter pylori could be linked to some other parameters such as bcl-2." (PMID 22216342, 2011). "Moreover, BCL-2 was associated with methotrexate resistance in gastric cancer cells." (PMID 33623790, 2021). "5′tRNA derivative tRF-Tyr competitively binds hnRNPD to modulate the c-Myc/Bcl2/Bax pathway, suppressing gastric cancer." (PMID 40565315, 2025). "The 5′tRNA derivative tRF-Tyr competitively binds hnRNPD to modulate the c-Myc/Bcl2/Bax pathway, suppressing gastric cancer." (PMID 40565315, 2025). "(2020) reported that usnic acid disrupted MMP and induced apoptosis via Bax : Bcl-2 imbalance and caspase activation in gastric cancer cells." (PMID 40469194, 2025). "DCA can also induce apoptosis of gastric cancer cells through mitochondrial pathway, which is manifested by the increase of Bax/Bcl-2 ratio and the collapse of mitochondrial membrane potential." (PMID 39897929, 2025). "Resveratrol induced apoptosis in gastric cancer cells via NF-κB down-regulation leading to a decrease in the level of anti-apoptotic factor Bcl-2 and an increase in apoptotic factors caspase-3 and caspase-8." (PMID 38689275, 2024). "-Inhibits IL-6 expression, induces JAK and STAT3 phosphorylation, and down-regulates STAT3-mediated protein Bad, Bcl-2, and Bax expression to treat gastric cancer." (PMID 38397559, 2024). "It is possible for the expression of Beclin1 and Bcl-2 to go out of balance in gastric cancer, which would limit autophagy and contribute to enhanced cell survival." (PMID 38887390, 2024).
gastric cancer (continued). "CircCCDC66 inhibited gastric cancer cell apoptosis by targeting miR-618 and BCL2, thereby reducing the sensitivity of gastric cancer cells to cisplatin." (PMID 39314750, 2024). "Overall, TCM induces apoptosis by modulating key proteins such as Bax, Bcl-2, caspase-3, and caspase-9 in both intrinsic and extrinsic pathways, thereby reducing tumor growth and demonstrating significant efficacy in gastric cancer treatment." (PMID 39906672, 2024). "UA (10–25 μM) applied to SNU-1 and AGS gastric cancer cells induced apoptosis, which was connected with increased Bax:Bcl-2, depolarization of the mitochondrial membrane and ROS elevation." (PMID 39457512, 2024). "Astragalus can reduce the angiogenesis of tumor and the invasive ability of gastric cancer cells, and can accelerate the process of apoptosis by high expression of Bcl-2 and low expression of Bax, partially inhibiting chromatin condensation and fragmentation." (PMID 38817861, 2024). "The results revealed that ibuprofen at 500 μM downregulated the transcription of the BCL2 gene in gastric cancer cells." (PMID 38792973, 2024). "In gastric cancer, Bcl-2 is often overexpressed, inhibiting apoptosis and promoting tumor progression." (PMID 39906672, 2024). "Specifically, it was observed that Bcl2-based drugs were observed to exhibit reduction in gastric cancer tumor size." (PMID 37736508, 2023). "Du and colleagues found that PVT1 can modulate the expression of anti-apoptotic Bcl2 and increase 5-FU resistance in gastric cancer." (PMID 37104009, 2023). "The levels of SNHG6 and Bcl-2 a known cell death inhibitor expression was found elevated in gastric cancer tissues in comparison to normal tissues." (PMID 37735423, 2023). "H. pylori-induced miR-21-mediated ASPP2 suppression confers resistance to apoptosis through inhibition of ASPP2/CHOP-mediated transcription of Noxa and Bak and suppression of Bcl-2 in gastric cancer cells." (PMID 37547633, 2023). "The role of the SNHG6/miR-1297/BCL-2 axis in regulating cisplatin resistance and progression of gastric cancer was studied." (PMID 37735423, 2023). "CM-DOP inhibited migration by reducing the expression of N-cadherin and vimentin, increasing E-cadherin, and promoting apoptosis through upregulating Caspase-3 and increasing the ratio of Bax/Bcl-2 on gastric cancer cells." (PMID 37894541, 2023). "A 4.25-fold decrease in the Bcl-xL/Bcl-2 ratio was achieved in gastric cancer cells compared with the untreated control upon anthocyanidin treatment." (PMID 35807546, 2022). "The expression of BCL-2 was the highest in the early stage of gastric cancer and decreased gradually during the development of cancer." (PMID 36313628, 2022). "ApoG2 suppressed the development and proliferation of gastric cancer cells through downregulation of Bcl-2 expression, upregulation of Bax, and increased activation of caspase-3." (PMID 36559116, 2022). "Solasonine was found to reduce the level of both Bax and Bcl‐2 in gastric cancer cells simultaneously, and decreased the Bax/Bcl‐2 ratio (about 2.1 folds)." (PMID 35524577, 2022). "Quercetin was found to arrest cell division by inducing cell cycle arrest at G0/G1 or G2/M phase in BGC-823 gastric cancer cells through protein analysis of Bax, Bcl-2, and caspases." (PMID 35237519, 2022). "It has been reported that HOXA10 deteriorates gastric cancer through inducing Bcl-2 expression and activating JAK1/STAT3 signaling pathway." (PMID 36407869, 2022). "In gastric cancer cell lines, artificial expression of miRNA-204 correlates with decreased BCL-2 regulation and inhibits colony formation and tumor cell migration." (PMID 35205839, 2022).